NQO1 (NAD(P)H quinone dehydrogenase 1)
Diseases named in the same sentence as NQO1 in open-access papers (continued):
Sharing a sentence is not in itself a finding about the gene and the disease.
tumor (continued). "While this is inconsistent with our observations that HIF-1α knockdown attenuated RKO xenograft growth compared with control and NQO1 overexpressed tumours, histological evaluation of these tumours showed reduced proliferation and increased apoptosis in HIF-1α-deficient xenografts." (PMID 27966538, 2016). "However, HIF-1α-positive areas were substantially expanded over the pimonidazole-positive hypoxic areas in NQO1-overexpressing tumours (RKO/pNQO1)." (PMID 27966538, 2016). "NQO1 is overexpressed in a variety of tumors compared to normal adjacent tissues, the characteristic of which confers an optimal window to develop anti-tumor agents with high selectivity towards tumor but sparing normal tissues." (PMID 27566573, 2016). "The most important result was that rGO + Arg strongly increased the expression of NQO1 in tumor tissue, which may have decreased the generation of reactive oxygen." (PMID 26512645, 2015). "Moreover, the strongly positiverate of NQO1 protein was significantly higher in NSCLC with T3-4 (>5 cm) tumor size than in cases with T1-2 (≤5 cm) tumor size (P = 0.005)." (PMID 25880877, 2015). "Therefore, UGT1A not only determines intracellular accumulation of β-lap, but more importantly can disrupt NQO1-triggered redox cycle that is the dominant mechanism for β-lap to elicit its anti-tumor efficacy." (PMID 25692465, 2015). "Moreover, the strongly positive rate of NQO1 protein was higher in NSCLCs with larger tumor size (>5 cm) than in cases with smaller (≤5 cm), and it was also significantly higher in poorly differentiated NSCLC than in moderately and well differentiated NSCLC." (PMID 25880877, 2015). "By combining NAMPT inhibitors (e.g., FK866) and NQO1 bioactivatable drugs (e.g., β-lap, ARQ761) we exploit the reliance of PDA on rapid NAD+ synthesis, as well as the tumor-selective overexpression of NQO1 through the use of agents that are bioactivated to induce cell death." (PMID 25590809, 2015). "Beyond these reports, however, the function of NQO1 in tumor progression remains controversial." (PMID 25885439, 2015). "Whole tumor homogenates were used to assay the HO-1 and NQO1 protein levels by Western blot." (PMID 26280276, 2015). "Furthermore, multivariate survival analysis demonstrated that NQO1 positive-expression was an independent prognostic factor along with tumor size, differentiation, lymph node metastasis and clinical stage." (PMID 25880877, 2015). "Results indicated that NQO1 status could be an important determining factor in tumour response to 17-AAG." (PMID 24886060, 2014). "Further investigation in tumour samples could shed light on whether this accurately reflects NQO1 expression in patients, or whether it is an artefact of a subset of cultured cell lines." (PMID 24886060, 2014). "Secondly, there are indications in the literature that cultured cell lines may express higher levels of NQO1 than lung and colon patient tumour tissue." (PMID 24886060, 2014). "However, high-level expression of NQO1 has been correlated with numerous human malignancies, suggesting a role in carcinogenesis and tumor progression." (PMID 24499631, 2014). "Given the biochemical properties of NQO1 in protecting cells from oxidative damage and tumor development, this result may be biologically plausible." (PMID 24884893, 2014). "In addition, β-lapachone toxicity was positively correlated with the expression and activity of NAD(P)H quinone oxidoreductase 1 (NQO1) in the tumor cells." (PMID 24505400, 2014). "In addition, it is interesting to note that in tumor tissues the expression of NQO1 is much higher while UGTs are lower than that in surrounding normal tissues." (PMID 24244442, 2013).
tumor (continued). "Thus, both in vitro and in vivo data strongly support that TSA is a promising specific NQO1 target anti-tumor agent." (PMID 22848731, 2012). "The present study aims to determine whether NQO1 plays a pivotal role on initiating the anti-tumor effect of TSA both in vitro and in vivo." (PMID 22848731, 2012). "The signaling pathways that we revealed in this study may significantly contribute to an improvement of NQO1-directed tumor therapies." (PMID 21738692, 2011). "This would make it more difficult to activate the new agent in cells with very low levels of NQO1, like bone marrow cells, but could still allow activation in tumor cells with higher levels of this enzyme." (PMID 21904446, 2009). "We compared the tumor cell growth inhibitory activity of BM analogs with sterically bulky groups of different size and placed at different positions on the benzoquinone ring, using tumor cell lines with different levels of NQO1." (PMID 21904446, 2009). "NQO1 has been used as a target for tumor specific drug development." (PMID 21904446, 2009). "Since m-nPrBM and p-PBM showed good tumor cell growth inhibition in the FaDu cells but poor activity in the T47D cells, these BM analogs would likely have good antitumor activity in tumors with high NQO1 activity but little activity in bone marrow cells." (PMID 21904446, 2009). "To test this hypothesis, we measured tumor cell growth inhibition produced by the series of BM analogs having different affinities for activation by NQO1, in human tumor cell lines with a wide range of NQO1 activity." (PMID 21904446, 2009). "We demonstrated that functional groups of different steric size could be used to produce a series of bioreductive antitumor agents that were activated by different levels of NQO1 in tumor cells." (PMID 21904446, 2009). "Human tumor cells have varied levels of NQO1 activity ranging from < 10 nmol." (PMID 21904446, 2009). "NQO1 activity is usually higher in tumour than normal cells, but is lower in vivo than in vitro." (PMID 15467770, 2004). "We showed previously that we could selectively increase NQO1 activity in tumour cells compared with normal cells and that this enhanced MMC antitumour activity in vitro." (PMID 15467770, 2004). "In this study we investigated whether we could selectively induce NQO1 activity in human tumours implanted in a nude mouse model, and if this would increase the antitumour activity of bioreductive agents without increasing the toxicity of these agents." (PMID 15467770, 2004). "We identified 9 genes whose increased expression was significantly associated with tumor size in female LC patients of which four code for MAPK signaling molecules (DUSP4, FGL1, TXNRD1, PLA2G4E), three for oncogenes (KRT16, STRIP2 and TNS4), tumor suppressor cystatin 5, and NQO1." (PMID 38245882, 2024). "Therefore NQO1 may be involved in the repair process of tumor DNA; thus, its expression may affect the levels of the tumor mutation burden and microsatellite instability." (PMID 37583897, 2023). "We next asked whether NQO1 expression has a role in primary tumor growth." (PMID 37169843, 2023). "However, the role of NQO1 is still unclear, NQO1 might function as either a pro-oncogenic or a tumor suppressor gene." (PMID 37188198, 2023). "Thus, the high expression of NQO1 in these cell types suggests its role in regulating tumor development by NQO1, possibly by influencing the extracellular matrix formation of these cells and the proliferation and extension of tumor cells." (PMID 37583897, 2023). "Therefore, it highlights the difficulties of assessing NQO1 using tissue homogenization techniques and the complexities of utilizing NQO1 as a therapeutic target, owing to the differential expression of this protein within the same tumor." (PMID 36359002, 2022).
tumor (continued). "Furthermore, knockdown of NQO1 in immune checkpoint inhibitor resistant tumours increased innate immune response to stimulate antitumour T cell adaptive immunity, and when retreated with checkpoint blockade therapies, eradicated therapy-resistant tumours." (PMID 34679751, 2021). "Moreover, NQO1 is frequently overexpressed in many tumor types, including lung and breast cancers." (PMID 34083537, 2021). "Meanwhile, the down‐regulation of NQO1 expression by limonin indicates that limonin may indirectly act on the apoptosis pathway through regulating the expression activity of internal antioxidant enzyme, thereby exerting its inhibitory effect on tumor cells." (PMID 33841805, 2021). "Perhaps, a combination approach with tumor-selective DNA damaging agents (e.g., NQO1-bioactivatable agents, vide infra in Section 6) may overcome this limitation to improve the tumor-selectivity of NAMPT inhibitors by severely depleting the NAD+ needed by PARPs for efficient DNA repair and survival." (PMID 32295316, 2020). "Besides, the study demonstrated that an abnormally high expression of NQO1 would promote phosphorylation level of X-linked inhibitor of apoptosis protein (XIAP) and enhance stability of XIAP protein, thereby inducing tumor growth and inhibiting apoptosis in HCC." (PMID 33083480, 2020). "Some studies have shown that Nrf2/NQO1 signaling pathway plays an important role in oxidative stress in respiration, digestion, nerve, cardiovascular system and other organs, and the expression level and activity of NQO1 are closely related to the occurrence and development of tumor." (PMID 31899687, 2020). "In addition, NQO1 activity appears to be increased during tumor progression." (PMID 31126053, 2019). "Moreover, it remains unclear whether the antitumor effect of THC and NQO1 inhibitor is due to the direct effect on tumor cells or indirect effect on microenvironment." (PMID 30737573, 2019). "This variant transcript was found in both normal and tumor tissues, although the corresponding protein could not be detected and recombinant NQO1 protein missing exon 4 was shown to have very low catalytic activity toward quinone substrates." (PMID 28883796, 2017). "Notably, tumor tissues usually bear much higher NQO1 but lower UGTs than in normal tissues." (PMID 25692465, 2015). "Notably, we previously reported that catalase (an essential enzyme for the detoxification of 2H2O2 to 2H2O + O2) expression was significantly downregulated in tumor tissue relative to normal tissue, and that the NQO1 to catalase ratio is markedly increased in tumor tissue." (PMID 26462257, 2015). "Similarly, strong staining was observed for NRF2 and NQO1 exclusively in the tumor cells and not the stroma in FH-associated Type 2 pRCC." (PMID 22014577, 2011). "If a series of bioreductive agents that were activated by different levels of NQO1 were available, a patient could be treated with an agent that was maximally activated by the level of NQO1 in their tumor but minimally activated by the level of NQO1 in their bone marrow." (PMID 21904446, 2009). "Thus, selectively increasing the level of NQO1 in tumour cells by gene transfer or by selective induction of NQO1 in tumours may be useful for enhancing the efficacy of bioreductive agents." (PMID 15467770, 2004).
tumor (continued). "Nrf2 pathway activation was assessed in PBMCs by measuring NAD(P)H:quinone oxidoreductase 1 (NQO1) mRNA expression, while tumor biopsies were examined via immunohistochemistry for markers related to inflammation, cell cycle progression, and apoptosis." (PMID 40732256, 2025). "This reveals that NQO1 activates the NF‐κB signaling pathway by reducing the ubiquitination of p65, which subsequently upregulates CXCL12 and promotes tumor progression." (PMID 41028931, 2025). "Only two pRCC PDC (300 and 195) showed a discrepancy between the tumour and the cell culture: while the NQO1 mRNA level and activity in the tumour were downregulated compared to the normal, the PDC showed increased NQO1 activity." (PMID 39707614, 2025). "Subsequent studies should evaluate the efficacy of NQO1 bioactivatable drugs, such as β-LPC and KP372-1, in selectively targeting tumor cells with high STEAP4 expression using patient-derived models and mouse models." (PMID 40205952, 2025). "After accumulating at the tumor site, CQG NPs deplete GSH and produce oxygen, which inhibits HIF-1α expression and reduces NQO1 and NRF2 levels, disrupting the antioxidant system in tumor cells." (PMID 40791799, 2025). "Other findings have indicated that certain antioxidant enzymes, such as NAD(P)H:quinone oxidoreductase (NQO1), play a role in promoting NET formation, as well as tumor progression and lung metastasis." (PMID 40725201, 2025). "Compared to the NQO1 group, the combined Plerixafor group indicated significantly increased infiltration of CD3+ T cells in the tumor tissue, while the infiltration of Treg cells (FOXP3+CD4+ and FOXP3+CD25+CD4+) was significantly reduced." (PMID 41028931, 2025). "Both combined treatment with cabozantinib + GDC‐0326 and CB‐839 monotherapy diminished the expression of NQO1, an NRF2 transcriptional target, in tumor cells." (PMID 40600748, 2025). "ScRNA‐seq data show that vitamin K cycle genes(NQO1, UBIAD1, GGCX, VKORC1, VKORC1L1) are specifically expressed in tumor cells." (PMID 41028931, 2025). "The activation of NQO1 can nullify the harmful effects of ROS on GBM cells, and thus, the overexpression of NQO1 significantly increases tumor growth." (PMID 40002465, 2025). "A β-lapachone β-glucuronideprodrug would take advantageof not only the target specificity imparted by NQO1 and 5-LO overexpressionin PDAC, but also the tumor-specific activation given by the expressionof β-glucuronidase." (PMID 41392458, 2025). "The unique feature of the trimethyl-locked quinone group is its ability to be reduced and removed by an enzyme called NAD(P)H quinone dehydrogenase 1 (NQO1), which is known to be overexpressed in tumor cells." (PMID 38773495, 2024). "NQO1, SLC1A4, and NOS2 were identified as potential genes in HB and found to be significantly upregulated in tumor samples." (PMID 37795447, 2023). "We found that stable depletion of NQO1 in A549 and H358 human NSCLC tumor models inhibits self-renewal capabilities, as demonstrated by a reduced ability to form primary, secondary, and tertiary spheroids." (PMID 36980879, 2023). "Mechanistically, NQO1 functioned as an agonist at pathways of PI3K/Akt and MAPK/ERK, which promoted HCC cell proliferation and tumor growth." (PMID 36959981, 2023). "Overall, these results support the suggestion that NQO1 is vital for NSCLC cells to grow in anchorage-independent conditions and supports the maintenance of the tumor-initiating cell population." (PMID 36980879, 2023). "In conclusion, these findings suggest that the anti-tumor mechanism of BRU and PD combined therapy inhibits Nrf2/HO-1 and NQO1 signaling pathways while increasing ROS levels, which has a toxic effect on BC cells and inhibits cell proliferation." (PMID 37175972, 2023). "On histologic evaluation, we further observed an increase in NQO1 and 4-HNE staining patterns at the tumor edge." (PMID 37752585, 2023).
tumor (continued). "NQO1 is highly expressed in human and mouse HCC cells, promoting proliferation and mediating tumor growth by activating the PI3K/AKT and MAPK/ERK signaling pathways, which suggests that NQO1 can be used as a therapeutic target for HCC." (PMID 37695786, 2023). "In patient RNA sequencing data, SLC7A11, NQO1, NFE2L2 and GCLM gene expression was higher in CRUK0772 tumour regions compared to CRUK0640." (PMID 38168428, 2023). "We speculate that mutation in B-Raf proto-oncogene may contribute, at least in part, to NRF2-mediated NQO1 overexpression to drive HCC development and that SFN treatment enhances oncogenic B-Raf-associated NRF2 activation, thereby up-regulating NQO1 expression to stimulate tumor growth." (PMID 35628208, 2022). "Multiplex immunofluorescence was performed to examine the co-localization of NQO1, NRF1 and NRF2 within the tumor and TME of 162 chemotherapy-naïve, early-stage NSCLC patients treated by primary surgical resection." (PMID 36359002, 2022). "NQO1 was overexpressed in NSCLC, and the knockdown of the NQO1 gene expression by its specific siRNA inhibited cell proliferation and tumor glycolysis metabolism in A549 cells by downregulating HK2 expression." (PMID 36532721, 2022). "Our results showed that NQO1 was correlated with the expression of the DNA repair gene NEIL3 (Pearson correlation coefficient), suggesting its role as a tumor control gene." (PMID 35308531, 2022). "We examined the GSH, SOD1, and NQO1 enzyme activity and GST levels in tumor and normal cells and found that these enzymes were at relatively higher levels in tumor tissues than in their corresponding adjacent normal tissues." (PMID 35945195, 2022). "Aiming to study the levels of known Nrf2 target genes in tumor and normal samples, we measured the total GSH levels and enzymatic activity of SOD1, NQO1, and GST levels in eleven primary tumors and adjacent normal tissues." (PMID 35945195, 2022). "CPSF6 is able to upregulate NQO1 to regulate HCC cell metabolism and thereby promote tumor development." (PMID 36211823, 2022). "NQO1, one of NRF2 target genes, is predominantly overexpressed in HCC tumor tissues and hence considered a prognostic factor of HCC." (PMID 35628208, 2022). "In the highly metastatic HSC3 subcutaneous tumor model, HOXA11-AS knockdown inhibited tumor growth by 25% more than lanthanide inhibition of ME1, a putative mediator of NQO1." (PMID 36142607, 2022). "Tumor cells associated with liver metastasis potential, but not those associated with lung metastasis potential, induced the methylation of metabolism genes including NQO1 and ALDH1a3 and subsequent downregulated mRNA expression of a broader group of metabolism genes in CAFs." (PMID 34727952, 2021). "Concomitant high NQO1 and low CAT mRNA levels (high NQO1:CAT ratios (p < 0.0001) in HCC tumor tissue offer an ideal target for NQO1 bioactivatable drugs." (PMID 34676172, 2021). "Our analysis revealed that the mRNA levels of NQO1 were significantly elevated (p = 1.5×10-7), while CAT levels were notably lower (p = 7.8×10-8) in tumor tissues than in matched normal tissues." (PMID 34676172, 2021). "This design of nanocatalytic system offers a new paradigm for combing PARP inhibitor, NQO1-bioactivatable drug and Fenton-reagents to obtain sustained H2O2 generation for tumor-specific self-amplified CDT." (PMID 34481495, 2021). "Among the top hits, we found NAD(P)H quinone dehydrogenase 1 (NQO1), a gene that was recently identified by our group as an important factor for aggressive tumor behavior and poor prognosis in HB." (PMID 32824198, 2020).